STAT3 (signal transducer and activator of transcription 3)
Diseases named in the same sentence as STAT3 in open-access papers (continued):
Sharing a sentence is not in itself a finding about the gene and the disease.
breast cancer (continued). "Here, the authors show that C-terminally phosphorylated p27, together with STAT3, mediates the transcriptional regulation of CSC expansion, increasing cancer formation and metastasis in preclinical breast cancer models." (PMID 38886396, 2024). "IL-6 expression is a critical step of breast cancer metastasis, leading to the activation of the JAK2/STAT3 signaling pathway that promotes proliferation, invasion, metastasis, and angiogenesis and inhibits apoptosis in breast cancers." (PMID 38673967, 2024). "The obtained NP efficiently decreased expression levels of STAT3, MMP2, MMP9 and VEGF, inhibited breast cancer growth, prolonged survival of animals, and reduced pulmonary metastasis three times." (PMID 38794298, 2024). "In breast cancer tissues, dual positivity for CXCR4 and phosphorylated STAT3 (p-STAT3) correlates positively with tumor size, lymph node metastasis, and histological grade." (PMID 38920657, 2024). "Within breast cancer stem cells, the HMGB1/TLR2/MyD88 axis governs NF-κB activation, IL-6 and TGF-β production, and the activation of STAT3 and Smad3." (PMID 38347830, 2024). "In breast cancer, chemotherapy activates the EZH2/STAT3 axis leading to the production of ExomiR-378a-3p and ExomiR-378d, resulting in chemotherapy-elicited, exosome-induced drug resistance." (PMID 38455764, 2024). "Lactate, for instance, a pivotal factor in driving macrophage M2 polarization to promote breast cancer progression, has been shown to activate ERK1/2 and STAT3 pathways in macrophages." (PMID 39003350, 2024). "By inhibiting the important oncogenic pathways STAT3, AKT, and ERK, silybin therapy of breast cancer cells resistant to doxorubicin/paclitaxel sensitized cells to chemotherapeutic drugs." (PMID 39125822, 2024). "We then analyzed the impact of stattic, a commonly used STAT3 inhibitor (it binds to the STAT3 SH2 domain and inhibits its activation), on TME Stimulation-induced pro-metastatic activities in HR+/HER2− breast cancer cells." (PMID 37190183, 2023). "To offer a glimpse into future clinical applications, we analyzed the gene expression of Pal targeted genes, CDK4 and CDK6, and Nif targeted genes STAT3 and CDK2 in breast cancer through the TNMplot database." (PMID 37752122, 2023). "It was later demonstrated that circRHOT1 induces ferroptosis by targeting signal transducer and activator of transcription 3 (STAT3) by sponging miR-106a-5p, thereby enhancing the invasion and metastasis of breast cancer cells." (PMID 37168995, 2023). "Tissue microarrays consisting of breast cancer specimens from a retrospective cohort (n = 850) were stained for IL6R, JAK1, JAK2 and STAT3 via immunohistochemistry." (PMID 37199043, 2023). "It strengthened the tolerance of breast cancer to DOX via binding and recruiting NF-κB to promote GATA3 transcription, further leading to the activation of STAT3." (PMID 37781691, 2023). "In turn, lactic acid triggers the HIF-1α/STAT3 axis in M2-like TAMs leading to the release of EGF and subsequent activation of EGFR/PI3K/AKT in breast cancer cells to elevate the expression of SGLT1 and promotion of drug resistance." (PMID 37900137, 2023). "Further functional experiments showed that the silencing of STAT3 reduced the proliferation, migration, and clonogenic survival of MDA-MB-231 breast cancer cells under hypoxic stimulation." (PMID 38067351, 2023). "Binding of ILEI to the LIF receptor (LIFR) activates STAT3 and leads to EMT and stem cell formation in a breast cancer model." (PMID 37226685, 2023). "The coactivation of STAT3 and NOTCH1 is associated with cisplatin resistance in HNSCC, and the simultaneous downregulation of STAT3 and NOTCH1 using siRNA enhances chemosensitivity in breast cancer." (PMID 37373457, 2023). "Increased MUC16 expression in breast cancer also promotes cell cycle progression (G2-M) and cell survival via JAK2/STAT3 signaling pathway." (PMID 36918912, 2023).
breast cancer (continued). "All these data indicate that PRRG4 via the STAT3-POLG pathway enhances the migration, invasion, and mitochondrial function of breast cancer cells." (PMID 38102641, 2023). "In addition, we previously noted that TrkB activates the IL6/JAK2/STAT3 signaling pathway in breast cancer via the formation of the TrkB/JAK2 complex and then induces the EMT program by upregulating Twist-1, suggesting that DJ-1 and TrkB may orchestrate to activate the STAT3 signaling pathway." (PMID 37749450, 2023). "In two stem-like breast cancer cell lines, induction of stemness can be performed by autophagy via the EGFR/Stat3 and TGFβ/Smad pathways in a murine model." (PMID 37190065, 2023). "Beta-END activates the survival/mitogenic signaling pathways (Akt, signal transducer and activator of transcription 3 (STAT3) and mitogen-activated protein kinases (MAPK)/extracellular signal-regulated kinase (ERK)) in human MDA-MB-231 breast cancer cells." (PMID 37509632, 2023). "CAFs secrete interleukin 6 (IL-6) which activates signal transducer and activator of transcription 3 (STAT3) signaling pathway, thus promoting the growth and radioresistance of breast cancer cells." (PMID 36635302, 2023). "Our results demonstrate that STAT3 inhibition significantly reduced PRRG4-induced increase in oxygen consumption and migratory behaviors of breast cancer cells." (PMID 38102641, 2023). "STA-21 and its structural analogs, LLL-3 and LLL-12, have shown selectivity for the SH2 domain of STAT3, inhibiting STAT3 dimerization and resulting in suppressed glioblastoma, BCR-ABL leukemias, OvCa, medulloblastoma, and breast cancer cell growth." (PMID 37173951, 2023). "In breast cancer cells, FGFR1 was shown to promote the synthesis of hyaluronan by activating STAT3 signaling." (PMID 38045829, 2023). "ZIC2 can transcriptional regulates Src, lncRNA SNHG12, Axin2, Runx2, OCT4, STAT3, PAK4 expression in non-small cell lung cancer, endometrial cancer, colon cancer, ccRCC, lung adenocarcinoma, liver cancer, and breast cancer 15, 28, 36-41." (PMID 37496990, 2023). "KLF14 suppressed breast cancer cell invasion and M2 macrophage polarization through modulating SOCS3/RhoA/Rock/STAT3 signaling." (PMID 38143751, 2023). "In this study, we have identified key roles for members of the STAT family, namely STAT3 and STAT1, in mediating PD-L1-induced cell-autonomous and pro-metastatic activities in breast cancer cells." (PMID 37830552, 2023). "IL-6 produced by CAFs stimulates the signal transducer and activator of transcription 3 (STAT3) pathway, promoting breast cancer cell growth and radioresistance." (PMID 37496657, 2023). "In breast cancer, LDLs were shown to affect cell growth and transformation induced by the JAK–STAT signaling pathway by regulating STAT3." (PMID 37900720, 2023). "JAK-2, STAT3, and STAT5 regulate genes that promote breast cancer cell survival, proliferation, and metastasis." (PMID 36674719, 2023). "In breast cancer lung metastasis, sevoflurane exposure during surgery primed the lung microenvironment via the IL6/JAK/STAT3 pathway." (PMID 37345096, 2023). "Leptin was also reported to activate the STAT3, AKT, and JNK pathways in breast cancer and ovarian cancer." (PMID 37488474, 2023). "Several transcriptional activators have been identified to regulate hTERT expression in breast cancer cells, including c-MYC, STAT3, NF-κB, ETS2, ERα, Sp1, KLF4, and ZEB1/YAP, among others." (PMID 37612721, 2023). "In the present study, we discovered 84 autophagy-related genes in macrophages incubated by breast cancer cell-derived exosomes induced by ferroptosis, including NLRP7 and STAT3." (PMID 36949762, 2023). "Parallel experiments that were performed with MDA cells provided additional evidence for the key roles played by STAT3 and STAT1 in mediating PD-L1 functions in breast cancer cells." (PMID 37830552, 2023).
breast cancer (continued). "Chronic stress promotes dissemination of breast cancer cells by remodeling lymph vasculature and epithelial to mesenchymal transition (EMT)-mediated metastasis of breast cancer through activation of STAT3 signaling pathway." (PMID 37773152, 2023). "In this study, we uncover that PRRG4 via the Src-STAT3-POLG axis enhances mitochondrial DNA copy number and ATP production, and promotes the migration and invasion of breast cancer cells." (PMID 38102641, 2023). "Other researchers simultaneously introduced STAT3 siRNA and methotrexate into MCF7 breast cancer cells using mesoporous silica nanoparticles functionalized with chitosan (chMSNs)." (PMID 38067351, 2023). "MID2, as a promoter of STAT3, is interacted with protein MORC4, which regulates DNA damage response and gene transcription in breast cancer." (PMID 36925638, 2023). "In HCC and breast cancer, IL6 from TAMs activates the STAT3 pathway to promote CSC population, migration, and angiogenesis." (PMID 38035101, 2023). "Furthermore, activator protein 1 (AP-1) and the signal transducer and activator of transcription 3 (STAT3) transcription factors have been recently identified in concert with the TEAD transcription factor as being important drivers of the YAP/TAZ transcription program in breast cancer." (PMID 37835407, 2023). "Inhibition of STAT3 signaling also reduces the expression of EMT inducers and MMPs in breast cancer cells." (PMID 37836626, 2023). "Further evidence found that the cGAS-STING pathway induces inflammatory response through IL-6, IL-6R and STAT3, and induces CD8+T cell infiltration to enhance anti-tumor immune responses in breast cancer." (PMID 37051596, 2023). "Both STAT3 and STAT4 were responsible for the transcription of IL12RB1 and IL12RB2 in breast cancer cell." (PMID 38107057, 2023). "Another research team developed a polyethyleneimine–polylactic acid–lipoic acid (PPL) micelle to simultaneously deliver STAT3 siRNA and paclitaxel (PTX) into the breast cancer model." (PMID 38067351, 2023). "This research direction was further enforced by studies demonstrating that STAT3 and STAT1 have cardinal roles in regulating cancer progression, including in breast cancer." (PMID 37830552, 2023). "Under the synergetic influence of dLAN and melatonin, the activated STAT3 inhibits DIRAS3 in an epigenetic manner, resulting in decreased autophagic activity and increased resistance of breast cancer to paclitaxel." (PMID 37190065, 2023). "One recent study demonstrates that narasin inhibits tumor metastasis and growth of ERα-positive breast cancer cells, and this is through inactivation of the TGF-β/SMAD3 and IL-6/STAT3 signaling pathways." (PMID 37864240, 2023). "Treatment with small molecules, such as 1′-acetoxychavicol acetate (ACA), plumbagin, and allicin, significantly inhibited STAT3 through induction of SHP-1 in several types of cancer cells, including breast cancer, gastric cancer, and cholangiocarcinoma." (PMID 38203502, 2023). "Together, the findings in this part of the study indicate that both STAT3 and STAT1 play key roles in mediating the cell-autonomous and PD-1-induced pro-metastatic functions of PD-L1 in breast cancer cells." (PMID 37830552, 2023). "Our findings demonstrated that VaM regulates Src and STAT3 through the involvement of SHP-1, leading to the induction of programmed cell death in breast cancer cells." (PMID 37569363, 2023). "Furthermore, TAMs activate the NF-κB/STAT3/ERK signaling pathway in tumor cells by secreting pro-inflammatory cytokines such as TNF-α and IL-6, which are responsible for the phosphorylation and activation of ERα, causing endocrine therapy resistance of breast cancer." (PMID 37900137, 2023). "Exosomal PTPRO induced the switch of macrophage polarization to the M1 phenotype mediated through the dephosphorylation, or inactivation, of STAT3 and STAT6 in inhibiting breast cancer invasion and migration." (PMID 36986884, 2023).
breast cancer (continued). "In summary, a membrane-biomimetic SDPN was developed for co-loading luteolin and silibinin, STAT3, and HIF 1-α inhibitors to alleviate breast cancer metastasis." (PMID 37403048, 2023). "Our results indicate that PRRG4 via the Src-STAT3-POLG axis enhances mitochondrial function and promotes migratory behaviors of breast cancer cells." (PMID 38102641, 2023). "Breast cancer-secreted IL-6 was found to orchestrate a chain of events, beginning with the upregulation of KDM2A in mammary fibroblasts through the STAT3/NFκB p50 axis." (PMID 37821959, 2023). "Therefore, in ER(−) breast cancer, p-STAT3 may be a useful poor prognostic factor." (PMID 35314590, 2022). "We found that Stattic (10 μM) greatly rescued the rhLIF-induced migration and invasion of breast cancer MDA-MB-231 and BT549 cells, and inhibited rhLIF-induced Stat3 phosphorylation in MDA-MB-231 and BT549 cells." (PMID 35280694, 2022). "Likely, LOC645166 has been revealed to recruit NF-κB to increase the transcription level of GATA binding protein 3 (GATA3), thereby inducing the STAT3 signaling pathway, which eventually facilitated ADR resistance in breast cancer cells." (PMID 36613528, 2022). "Therefore, the clinical role of STAT3 breast cancer remains unclear." (PMID 35314590, 2022). "To summarize, the IL-6/JAK/STAT3 signaling pathway mediates breast cancer progression, metastasis, and therapeutic resistance thus justifying investigations into IL-6/JAK/STAT3 as a targeted therapy for breast cancer patients." (PMID 35371975, 2022). "In an orthotopic allograft model incorporating breast cancer stem cell-enriched TNBC tumors, SL-145 potently suppressed tumor growth, angiogenesis, and metastases concomitant with dysregulation of the JAK2/STAT3 signaling pathway." (PMID 35501463, 2022). "For instance, in the context of breast cancer cells, PKM2 expression can be regulated through a feedback loop formed by let‐7a‐5p, Stat3, and hnRNP‐A1 to modulate glucose metabolism." (PMID 35349748, 2022). "Recent reports indicated that SHC1 was a key driver of breast cancer initiation, and the SHC1 adaptor simultaneously balanced Stat1 and Stat3 activity to promote breast cancer immune suppression." (PMID 35935986, 2022). "Consistent with the previously published results for breast cancer cells, nintedanib reduced the phosphorylation of JAK2 and STAT3 in senescent HDFs." (PMID 36055997, 2022). "Withaferin A activity has been found to modulate the JAK/STAT pathway in human breast cancer cells by decreasing phosphorylation of STAT3 and JAK2 in MDA-MB-231 breast cancer cell line." (PMID 36339589, 2022). "Then, the Transwell migration and Matrigel invasion assays showed that the knocking down of endogenous Stat3 can reverse the promotion of rhLIF and CAA-CM on breast cancer cell migrationand invasion." (PMID 35280694, 2022). "A derivative of these compounds has been found to have a very high affinity to STAT3 SH2 (IC50 of 162 nM), and to inhibit the STAT3 phosphorylation, essential for its dimerization-dependent function(s), at 100 nM in MDA-MB-468 breast cancer cell line." (PMID 36555586, 2022). "However, in breast cancer, the clinical role of STAT3 remains unclear." (PMID 35314590, 2022). "In addition, Huiming Zhang and his colleague 73 discovered that circRHOT1 could attenuate cancer cell ferroptosis through the miR-106a-5p/STAT3 pathway and promote the invasion and migration of breast cancer cells, leading to worsening progression of breast cancer." (PMID 35342359, 2022). "Inhibiting autophagy in triple-negative breast CSCs inhibited the STAT3/JAK2 pathway-mediated production of IL-6, a cytokine critical for CSC survival and required to produce the CD44+/CD24low phenotype in breast cancer cell lines." (PMID 35800881, 2022). "Collectively, treatment with S6 inhibited STAT3 phosphorylation and attenuated the downstream TGF-β/KRAS signaling pathways, which in turn inhibited breast cancer progression." (PMID 36581888, 2022).
breast cancer (continued). "Herein, we summarize the biology of the IL-6 signaling pathway, its roles in breast cancer metastasis, and therapeutic advancements in targeting the IL-6/JAK/STAT3 signaling axis." (PMID 35371975, 2022). "Among the breast cancers, the breast cancer cells recruit MDSC using cytokines and chemokines via three pathways, STAT3/IRF-8, PTEN/Akt and STAT3-NF-κB-IDO, to suppress anti-tumor immune responses and facilitate cancer cell proliferation." (PMID 36439106, 2022). "Given that the IL-6/JAK/STAT3 signaling axis promotes metastatic phenotypes of breast cancer, researchers have investigated the role of IL-6/JAK/STAT3 in breast cancer metastasis in vivo to identify key drivers and therapeutic interventions." (PMID 35371975, 2022). "Aberrant activation of the JAK/STAT3 pathway due to down-regulation of SOCS1 by miR-155 is observed in solid tumors, such as breast cancer and laryngeal carcinoma." (PMID 36505769, 2022). "Silencing STAT3 impaired FAO and inhibited self-renewal, whereas stimulating FAO by bezafibrate rescued self-renewal in breast cancer stem cells." (PMID 35646898, 2022). "Mechanistically, miR-155 overexpression in breast cancer cells upregulated their CXCL9/10/11 production, which was mediated by SOCS1 inhibition and increased phosphorylated STAT1 (p-STAT1)/p-STAT3 ratios." (PMID 35925680, 2022). "In a mouse model of breast cancer, this nano-emulsion inhibited CXCR4 and STAT3 expression with significant anti-metastatic activity." (PMID 35893797, 2022). "For example, FAs released from adipocytes are transported into breast cancer cells via CD36, which in turn induces EMT and stem cell properties in breast cancer cells by activating STAT3 signaling." (PMID 36354702, 2022). "This indicates that breast cancer cells upregulate OPG in breast stromal fibroblasts through the IL-6 protein and its canonical STAT3 pathway." (PMID 36359766, 2022). "In breast cancer, NIC reverses the adipocyte-induced epithelial–mesenchymal transition (EMT) in breast cancer cells by inhibiting the interleukin-6/STAT3 signaling axis, thus inhibiting cell migration and invasion ability." (PMID 36555754, 2022). "That NO is relevant to CSCs at all was first suggested in breast cancer, where NO increased expression of CD44 and of signal transducer and activator of transcription 3 (STAT3)." (PMID 36289675, 2022). "IL-6 is also known to promote breast cancer invasion to the bone, upregulating the chemokine receptor CXCR4 via STAT3 signaling in breast cells to promote proliferation of breast cells to the bone matrix." (PMID 35053592, 2022). "The hypoxia microenvironment can promote the expression of stem cell markers in breast cancer, activate the JAK2/STAT3 signaling pathway and increase the fatty acid oxidation level to maintain its stemness." (PMID 36497050, 2022). "In fact, many breast cancer cell lines produce IL6, which activates STAT3 by signaling through the IL-6 receptor and Jak kinases." (PMID 35327992, 2022). "Except for the five genes ITPK1, RIPK3, STAT3, TNF, and FASLG, the remaining 62 genes showed significant differences in expression between breast cancer and normal breast samples." (PMID 36675706, 2022). "The basic pathways of autophagy-dependent CSC maintenance have been demonstrated to occur via the EGFR/Stat3 and TGF/Smad pathways in breast cancer stem-like cells." (PMID 35800881, 2022). "ROS is a key factor in maintaining the stemness of CD44+ breast cancer cells through upregulating the expression of CD44 and signal transducer and activator of transcription 3 (STAT3)." (PMID 36497050, 2022).